RNU6-336P (RNA, U6 small nuclear 336, pseudogene)
Gene: Small nuclear RNA gene on chromosome 8 (22,434,391 to 22,434,497, forward strand). Ensembl gene ENSG00000201761.
Homologues: Orthologues: chimpanzee U6 (100% identical), macaque U6 (94% identical), pig U6 (81% identical), dog U6 (78% identical), guinea pig U6 (74% identical), guinea pig U6 (69% identical), dog U6 (68% identical), guinea pig U6 (66% identical). Paralogues in human: RNU6-1287P (83% identical), RNU6-1060P (82% identical), RNU6-1243P (82% identical), RNU6-797P (82% identical), RNU6-879P (82% identical), RNU6-1050P (81% identical), RNU6-24P (81% identical), RNU6-543P (81% identical), RNU6-1019P (80% identical), RNU6-1073P (80% identical), RNU6-1123P (80% identical), RNU6-1147P (80% identical), and 1285 more.